INS (insulin)
Diseases named in the same sentence as INS in open-access papers (continued):
Sharing a sentence is not in itself a finding about the gene and the disease.
Insulin resistance (continued). "Beta-cells respond to hepatic insulin resistance in the early stages of T2DM development by boosting insulin secretion, elevating basal insulin levels, and reinforcing the liver cycle." (PMID 36819346, 2023). "Fasting insulin and HOMA-IR which are considered as markers of insulin resistance are slightly elevated in GDM mothers as compared to controls, though it was not statistically significant in our study." (PMID 36873578, 2023). "Next, because mitochondrial function is often altered during insulin resistance, we assessed the effect of JPH on mitochondrial function in both insulin-sensitive and insulin-resistant cells." (PMID 37367923, 2023). "In rats fed the cafeteria diet, plasma insulin and HOMA-IR were significantly higher than in Standard animals, indicating diet-related insulin resistance." (PMID 37571269, 2023). "Curcumin treatment reduced fasting blood glucose (FBG), fasting insulin (FINS), and homeostatic model assessment of insulin resistance (HOMA-IR) in DHEA-treated Sprague-Dawley female rats." (PMID 37346347, 2023). "Homeostatic model assessment of Beta cells function (HOMA‐B), homeostatic model assessment insulin resistance (HOMA‐IR), homeostatic model assessment insulin sensitivity (HOMA‐% S), and disposition index (DI) of the experimental rats." (PMID 38107117, 2023). "Meanwhile, we selected FPG, OGTT 2 h glucose, HbA1c, fasting insulin, HOMA-IR, and HOMA-β as indicators that are commonly used in clinical practice to assess glucose metabolism and insulin resistance." (PMID 37564380, 2023). "We then used the homeostasis model assessment of insulin resistance index (HOMA-IR), a simple and effective method for evaluating insulin sensitivity, to evaluate the level of insulin resistance." (PMID 37627914, 2023). "As suggested by the differences in fasting insulin concentrations, LIRA and GH + LIRA rats were protected against the development of insulin resistance." (PMID 36480511, 2023). "Glucose and insulin fasting serum levels were obtained and the HOMA-IR was calculated; insulin resistance was diagnosed in cases with a HOMA-IR value over 2.1." (PMID 37626790, 2023). "CRP in pregnancy and in the early postpartum predicted higher insulin resistance: both higher hepatic insulin resistance (HOMA-IR) and lower whole body insulin sensitivity (MATSUDA) at 1-year postpartum." (PMID 37891561, 2023). "It has been demonstrated that BA, administered via the intestine, indirectly improved insulin resistance through the secretion of GLP-1 and insulin, with the participation of gut microbiota." (PMID 37291645, 2023). "Other methods for assessing IR include the Quantitative Insulin Sensitivity Check Index (QUICKI) and Fasting Insulin Resistance Index (FIRI)." (PMID 37775762, 2023). "Brain insulin resistance in HFD-fed mice at molecular levels was confirmed by the reduced expression of insulin receptors and molecules involved in insulin signaling, such as Akt/p-Akt." (PMID 36902167, 2023). "Dexamethasone treatments prevent translocation of GLUT-4 to the cell surface via altering insulin signaling pathway by inhibiting phosphatidylinositol-3-kinase (PI3K) and serine/threonine protein kinase and induces insulin resistance." (PMID 37447192, 2023). "For example, insulin can sensitize TRPV1 channels in sensory neurons of the pancreas, while TRPV1 antagonists can increase insulin secretion and improve insulin resistance in diabetic mice." (PMID 38983093, 2023). "This suggests that aside from protein abundance and insulin signaling to GSK3, other factors that control GSK3 are likely disrupted during insulin resistance." (PMID 36808134, 2023). "Thus, in hypoinsulinemia, the absence of insulin action on PPF neurons may indicate the development of insulin resistance, while the effect of insulin on PPD neurons indicates its ability to recover the form of plasticity to the control level in normoinsulinemia." (PMID 37025701, 2023).
Insulin resistance (continued). "Curcumin has also been shown to improve insulin resistance and glucose tolerance in db/db mice and HFD-fed mice, as well as to increase insulin levels in db/db mice." (PMID 37759802, 2023). "We found a significant inverse relationship between the expression of the SIRT1 gene and insulin levels, as well as the HOMA-IR index, which implies that SIRT1 plays a substantial role in regulating insulin resistance." (PMID 37862340, 2023). "Given that xanthurenic acid interferes with the synthesis of insulin in β-cells and creates inactive complexes with insulin, it could be part of the last protective mechanism that acts against hyperinsulinemia and insulin resistance and reflects the severity of the diabetic disorder." (PMID 37929025, 2023). "Since hyperglycemia and insulin resistance are characteristics of T2DM, therapeutic agents or inhibitors that reduce postprandial hyperglycemia and hyperinsulinemia and improve insulin sensitivity have been used to treat T2DM." (PMID 37107213, 2023). "Of note, adipose-derived TNF-α and IL-6 are crucial adipokines that suppress adipocyte insulin sensitivity and even lead to insulin resistance by attenuating insulin receptor-substrate 1 (IRS-1), which is a necessary component of insulin signaling." (PMID 37555019, 2023). "Subsequent studies have also demonstrated that circulating FGF21 is closely related to muscle insulin resistance, and FGF21 levels are increased under conditions of hyperinsulinemia or decreased insulin sensitivity in muscle." (PMID 38069273, 2023). "GH2 promotes maternal insulin resistance, whereas PRL promotes insulin secretion to compensate for the increase in maternal insulin resistance during pregnancy." (PMID 37049394, 2023). "Insulin resistance in the liver is mainly involved with the defective signaling transduction of PI3K-AKT and Ras-MAPK pathway resulted in insulin and glucose tolerance, further leading to the accumulation of TG and aggravating the development of NAFLD." (PMID 36410795, 2023). "Further investigations are warranted to identify possible additional effects of this locus on insulin resistance, possibly via impact on SLC36A4, as well as insulin secretion through MTNR1B." (PMID 37291194, 2023). "Metabolic dysfunction presented as hyperinsulinemia, insulin resistance assessed by HOMA‐IR, decreased hepatic insulin extraction, and hyperglucagonemia as sign of glucagon resistance." (PMID 37078380, 2023). "Rats developing insulin resistance due to HFD feeding showed more active GLP-1 and insulin in plasma." (PMID 37175192, 2023). "Supplemental WG reduced (PWG= 0.016) serum fasting insulin by at least 27% and significantly (PWG = 0.006) improved the insulin resistance marker, HOMA-IR by at least −29%." (PMID 37181127, 2023). "To better analyze insulin sensitivity in the liver, we measured the P-IRS1(Ser307) protein levels, being Ser307 phosphorylation related to insulin-resistance." (PMID 36875756, 2023). "Regarding the insulin-resistance markers, HOMA based on fasting insulin or C-peptide decreased in both groups, but the differences were not significant." (PMID 37685355, 2023). "Mechanistically, BACH1 directly interacted with PTP1B and IR-β in hepatocytes, and loss of hepatic BACH1 reduced the interaction between PTP1B and IR-β upon insulin stimulation in HFD-fed mice, thus improving insulin resistance and glucose metabolism." (PMID 38129407, 2023). "The potent pan-IP6K inhibitor LI-2242 ameliorates obesity, insulin resistance, and hepatic steatosis in DIO mice via a specific reduction in body fat and the improvement of insulin sensitivity." (PMID 37238737, 2023). "Serum insulin was significantly higher in mice injected at ZT23 particularly during the dark phase, indicating insulin resistance in these mice, although NAD+ therapy was effective to reduce fasting serum glucose independently of the time of supply." (PMID 36973248, 2023).
Insulin resistance (continued). "While a direct link between insulin BBB transport and CNS insulin resistance has not been established, this data points to a connection between insulin BBB transport and the development of CNS insulin resistance." (PMID 37076875, 2023). "In fact, the treatment of insulin resistance is a therapeutic approach for NAFLD, and insulin-sensitizing drugs such as thiazolidinediones have been prescribed to patients with NAFLD." (PMID 37176029, 2023). "For terrestrial animals, miR-29a interferes with insulin signal transduction mainly through the PI3K/AKT pathway and plays a crucial role in the process of insulin resistance." (PMID 37091861, 2023). "This, in turn, leads to IL-1β and IL-18 secretion and subsequent insulin resistance through serine phosphorylation of IRS-1 and impairment of insulin signaling." (PMID 37372020, 2023). "PCOS patients generally have insulin resistance, and IGF1 can enhance pancreatic β cell viability and inhibit apoptosis by activating the Sirt1/PI3K/Akt/FoxO1 pathway, inducing insulin secretion, and alleviating oxidative damage." (PMID 37701184, 2023). "To evaluate the role of miRNAs in the insulin resistance mechanism in T2DM, we analyzed the relationship between the expression of free plasma miRNAs and the insulin resistance (HOMA-IR) and insulin sensitivity (HOMA-S) indices." (PMID 37786444, 2023). "Insulin resistance, one of the hallmarks of NAFLD, increases the secretion of insulin and insulin-like growth factor (IGF)-1." (PMID 36831649, 2023). "The TyG index is considered a cost-effective and efficient indicator of insulin resistance compared to other methods like Homeostatic Model Assessment for Insulin Resistance (HOMA-IR), as it eliminates the need for measuring insulin levels." (PMID 37881497, 2023). "UDCA is a bile acid monomer that can lower insulin resistance in T2DM, and when used as a protective insulin carrier, it imparted the dual property of being a bile acid receptor agonist to improve insulin absorption." (PMID 37765234, 2023). "Acute GSK3 inhibition partially restored insulin sensitivity in these models, implicating GSK3 dysregulation as a mediator of adipocyte insulin resistance." (PMID 37248992, 2023). "For epidemiological purposes, one of the methods most widely used is the Homeostasis Model Assessment of Insulin Resistance (HOMA-IR), which is highly correlated with the clamp technique and is calculated using fasting plasma glucose and serum insulin levels." (PMID 36771304, 2023). "In the Strong Heart Family Study, sphingolipids were evaluated with both baseline and follow-up analyses of plasma insulin, HOMA of insulin resistance (HOMA-IR) and HOMA of β-cell function (HOMA-B) after adjustment for risk factors." (PMID 37237968, 2023). "Consistent with the presence of insulin resistance observed after the ITT, all treatments increased plasma insulin levels compared with the control." (PMID 37229459, 2023). "Such diets have shown decreased homeostatic model assessment for insulin resistance (HOMA-IR), fasting insulin levels, total and low-density lipoprotein (LDL) cholesterol, triglycerides, waist circumference, and total testosterone." (PMID 37762856, 2023). "The Homeostatic Model Assessment of Insulin Resistance (HOMA-IR), based on fasting glucose and insulin level products, is the most widely used method for IR characterization." (PMID 37835767, 2023). "This suggested that the two paradigms model different stages of T2D, with WD representing prediabetes with pronounced peripheral insulin resistance and WD + STZ representing later stages of T2D with the additional characteristic of impaired insulin secretion." (PMID 37885804, 2023). "For example, correlations of the insulin sensitivity index (SI from the FSIGT) and HOMA-IR are − 0.73 and − 0.62 for Mexican Americans and African Americans, respectively, in the Insulin Resistance Atherosclerosis Family Study (IRASFS)." (PMID 37558891, 2023).
Insulin resistance (continued). "Regarding insulin/glucose responsiveness, we evaluated the fasting insulin (FINS) and homeostatic model assessment of insulin resistance (HOMA‐IR)." (PMID 37576042, 2023). "One of the major signaling pathways involved in the development of FFA-induced liver insulin resistance is the c-Jun N-terminal kinase (JNK) pathway, which contributes to the disruption of insulin signaling and promotes cell damage (lipoapoptosis)." (PMID 38068822, 2023). "Indicators of insulin resistance (IR), such as fasting blood glucose (FBG) and serum insulin levels, were also significantly higher in the MetS and T2DM groups." (PMID 37342535, 2023). "As brain insulin resistance is a common feature of those with dementia, including AD, it further supports the role of the BBB in brain insulin resistance." (PMID 37076875, 2023). "All these pathways hinder insulin-induced tyrosine phosphorylation and PI3K-AKT activation, resulting in insulin resistance." (PMID 37958572, 2023). "Our study confirmed that HFD induces an increase in body weight, hyperglycemia and insulin resistance in APP/PS1 mice accompanied by the downregulation of IRS2 protein levels in the liver, a protein involved in insulin signaling regulation." (PMID 36895036, 2023). "We evaluated insulin resistance using the Homeostatic Model Assessment of Insulin Resistance (HOMA-IR) test, which is widely used in clinical research, but the hyperinsulinemic–euglycemic clamp is considered the gold standard for assessing insulin action." (PMID 37512005, 2023). "Additionally, short sleep duration may decrease melatonin secretion and trigger systematic inflammation, potentially disrupting glycemic control through a variety of pathways, including insulin resistance, reduced insulin sensitivity, and impaired glucose tolerance." (PMID 38027156, 2023). "There exists a significant association between decreased levels of PLP and elevated fasting insulin and HOMA-IR readings, indicating a distinct correlation between inadequate vitamin B6 levels and insulin resistance in individuals with type 2 diabetes." (PMID 38313181, 2023). "Consequently, the statin‐mediated decrease in β‐cell insulin production may not be the complete mechanism underlying the effect of rosuvastatin on glucose metabolism and insulin resistance." (PMID 37139700, 2023). "When overviewing the natural history of T2DM, the insulin resistance transforms primarily into prediabetes and then into overt T2DM when insulin secretion is insufficient to maintain glucose levels within the normal range." (PMID 37445466, 2023). "Of the markers describing insulin resistance, HOMA2-IR index was found to be related to the same glycan structures as fasting insulin—GP21 and GP6 (padj = 6.572x10-03 and 2.08x10-02, respectively)." (PMID 37079606, 2023). "On HFHSD, insulin tolerance test (ITT)showed significantly higher blood glucose levels of Aldh2 KI and HE mice than WT mice, indicating increased insulin resistance." (PMID 37749090, 2023). "By applying HOMAs to identify diabetic pigs, the insulin and blood glucose parameters indicated that the LEPTIN−/− pigs were insulin resistance by 12-months of age, with reduced insulin sensitivity and islet β cell function." (PMID 37705071, 2023). "It is well recognized that fasting hyperglycaemia represents predominantly hepatic insulin resistance, while post-prandial glucose excursions (and glucose excursions during OGTT) represent predominantly peripheral insulin resistance." (PMID 37049439, 2023). "IFC further appears more specific to the post-challenge insulin resistance observationally, with IFC being more strongly correlated than ISI with 2 h measures of insulin and glucose in the Fenland Study." (PMID 37291194, 2023). "In particular miR-15b was suggested to contribute to development of future insulin resistance by downregulation of the insulin receptor and upregulation of PI3KR1, leading to impaired insulin signaling." (PMID 38288471, 2023).
Insulin resistance (continued). "Nevertheless, when assessing insulin resistance through the homeostasis model assessment for insulin resistance (HOMA-IR index), we observed reduced insulin sensitivity in overfed rats compared to controls." (PMID 37833890, 2023). "The metabolic score for insulin resistance (METS-IR) is a simple, convenient, and reliable marker for resistance insulin (IR), which has been regarded as a predictor of cardiovascular disease (CVD) and cardiovascular events." (PMID 37461067, 2023). "Obese subjects with insulin resistance (higher HOMA-IR and lower oral glucose insulin sensitivity index) had higher expressions of DKK1, DKK2, sclerostin, and sFRP-1 but lower expression of osteogenic microRNA and β-catenin." (PMID 37569816, 2023). "Compared to age- and BMI-matched controls, normal-weight PCOS women as determined by the NIH criteria also exhibit adipose insulin resistance (adipose-IR; defined by the product of fasting circulating free fatty acid (FFA) and insulin levels)." (PMID 37834765, 2023). "The present study aimed to investigate the association between the progression of IR, assessed by the Homeostasis Model Assessment of Insulin Resistance (HOMA-IR), and the HDL subfraction profile in 377 samples (240 control and 137 insulin-resistant subjects)." (PMID 37686368, 2023). "For instance, insulin and insulin-like growth factor-I (IGF-I) reduced T688 phosphorylation in neuronal cultures from healthy rats and in a mouse model of insulin resistance and metabolic syndrome that exhibited cognitive decline." (PMID 38203429, 2023). "We assessed clinical parameters, including insulin activity, GSH, MDA, uric acid, and lipid profile, across subjects in the non-insulin resistance group." (PMID 38107710, 2023). "Animal models of insulin resistance showed memory deficit and a decrease in GLUT4 and hippocampal insulin signaling." (PMID 36969810, 2023). "To determine the target organ responsible for insulin resistance, we tested the phosphorylation level of AKT (pAKT) in eWAT, iWAT, liver, skeletal muscle, and BAT 10 min after insulin injection in HFD-fed mice." (PMID 37734559, 2023). "AdipoRaMab treatment also significantly reduced insulin levels in the fasting state and during the OGTT, as well as in the insulin resistance index." (PMID 37948516, 2023). "However, after adjustment for insulin, the association was not significant, suggesting that insulin resistance may be one of the main mechanisms linking glucose and cholesterol metabolism." (PMID 37686841, 2023). "Additionally, both isolated adipocytes and myocytes exposed to H2O2 demonstrate impaired PKB activation and markers of insulin-signaling, while conversely the use of antioxidants (e.g. lipoic acid or N-acetylcysteine) prevent the induction of insulin resistance." (PMID 37153211, 2023). "A total of 107 subjects had insulin resistance (HOMA-IR, 5.9±1.1) whereas 90 subjects had insulin sensitivity (HOMA-IR, 1.06±0.39)." (PMID 37809190, 2023). "In our analysis of 3T3-L1 models of adipocyte insulin resistance, we detected multiple insulin signaling alterations shared across different models, leading us to hypothesize that pharmacological targeting of any one of these alterations may only confer a partial reversal of insulin resistance." (PMID 36808134, 2023). "Insulin-mediated suppression of lipolysis, elevated FFA levels and glucose production and severe insulin resistance are common in GDM." (PMID 37627482, 2023). "In summary, RYGB resulted in reduced hepatic VLDL1 production that correlated with reduced insulin resistance, elevated VLDL2 clearance, and improved insulin sensitivity in lipoprotein lipolysis pathways." (PMID 37432744, 2023). "Fasting glucose and insulin levels, and the insulin resistance index (HOMA-IR), were markedly lower in TcMAC21 mice relative to euploid controls, indicative of enhanced insulin sensitivity." (PMID 37249575, 2023).